RN7SL248P (RNA, 7SL, cytoplasmic 248, pseudogene)
Synonyms: RN7SL527P
Gene: Miscellaneous RNA gene on chromosome 10 (46,648,948 to 46,649,276, forward strand). Ensembl gene ENSG00000274186.
Homologues: Orthologues: chimpanzee Metazoa_SRP (99% identical), macaque Metazoa_SRP (95% identical). Paralogues in human: RN7SL453P (100% identical), RN7SL733P (98% identical), RN7SL33P (70% identical), RN7SL487P (68% identical), RN7SL775P (67% identical), RN7SL40P (67% identical), RN7SL526P (65% identical), RN7SL1 (65% identical), RN7SL317P (65% identical), Metazoa_SRP (65% identical), RN7SL2 (65% identical), RN7SL3 (64% identical), and 701 more.